FASN (fatty acid synthase)
Diseases named in the same sentence as FASN in open-access papers (continued):
Sharing a sentence is not in itself a finding about the gene and the disease.
endometrial adenocarcinoma (3 papers, 2017 to 2023). "FASN expression is purported to be part of the estrogen-driven cellular response that leads to proliferation, and inhibiting FASN in endometrial adenocarcinoma cells acts as an antagonist, reducing E2- and tamoxifen-dependent estrogen receptor (ER) transcriptional activity." (PMID 37958433, 2023).
endometriosis (3 papers, 2022 to 2024). The growth of functional endometrial tissue in anatomic sites outside the uterine body. "We noted that a KO related to the long-chain saturated fatty acids biosynthesis, a metabolic pathway catalyzed by fatty acid synthase (FASN) was increased in women with endometriosis." (PMID 39020289, 2024).
endothelial dysfunction (3 papers, 2012 to 2023). In vascular diseases, endothelial dysfunction is a systemic pathological state of the endothelium (the inner lining of blood vessels) and can be broadly defined as an imbalance between vasodilating and vasoconstricting substances produced by (or acting on) the endothelium. "Previous studies demonstrated that FASN modulated endothelial dysfunction in hypoxic pulmonary artery endothelial cells." (PMID 36922854, 2023).
epidermoid carcinoma (3 papers, 2009 to 2022). "Finally, we demonstrated that p63 and FASN expression are positively associated in clinical squamous cell carcinoma samples as well as in the developing prostate." (PMID 19517019, 2009). "Overexpression of FASN as well as p63 has been previously demonstrated in squamous cell carcinomas from various organs." (PMID 19517019, 2009).
fibrosis (3 papers, 2020 to 2023). the formation of excess fibrous connective tissue in an organ or tissue in a reparative or reactive process. "Here, we confirmed that FASN protein levels were decreased in the lungs of human patients with IPF and in BLM-induced fibrosis mice." (PMID 37270622, 2023).
head and neck cancer (3 papers, 2012 to 2023). A primary or metastatic malignant neoplasm affecting the head and neck. "In addition, overexpression of crucial components in lipid metabolism, such as cluster of differentiation 36 (CD36), fatty acid-binding protein (FABP), acetyl-CoA carboxylase (ACC), and fatty acid synthase (FASN), have been well-documented in head and neck cancer." (PMID 37927468, 2023).
hepatitis C (3 papers, 2010 to 2017). "In a similar imaging study, an alkyne-functionalized analog of Orlistat, a β-lactone-based covalent inhibitor of fatty acid synthase (FASN), was used to image the localization of FASN during Hepatitis C Virus infection." (PMID 24473203, 2014). "This is prompted both by the significant, genotype independent association we found between CB1 expression and viral load, and by reports that blockade of the SREBP and FASN signalling in hepatitis C cell culture models reduces HCV replication." (PMID 20862263, 2010). "In hepatitis C, hepatitis C virus (HCV) infection not only upregulates the expression of fatty acid synthase but also attenuates mitochondrial β-oxidation through down-regulation of mitochondrial trifunctional protein (MTP)." (PMID 28496435, 2017).
Hypercholesterolemia (3 papers, 2017 to 2023). An increased concentration of cholesterol in the blood. "The explanation for the increased overall fatty acid level observed in isolated hypercholesterolemia is not clear and should be investigated in separate studies, since we have not found increased FASN expression in our study." (PMID 28750643, 2017).
Hypertension (3 papers, 2016 to 2024). The presence of chronic increased pressure in the systemic arterial system. "The enzyme FASN (fatty acid synthase) is potentially related with hypertension and metabolic dysfunction." (PMID 27090298, 2016).
ischemic stroke (3 papers, 2022 to 2023). A stroke disorder caused by obstruction of blood flow to the brain, due to thrombotic (local blood clot formation) or embolic (due to a blood clot or other material traveling from another site) event. "We found that GTA administration during the subacute phase of ischemic stroke increased the level of free lauric acid, an intermediate product for lipogenesis under FASN catalysis, indicating that GTA enhanced FASN-driven lipogenesis in the peri-infarct area after intragastric administration." (PMID 37968698, 2023). "Among the gene targets of miR-486-3p, FASN has been reported as a critical mediator in de novo lipogenesis in astrocytes following cerebral ischemic injury, while SYK is involved in cerebral inflammatory activation after ischemic stroke." (PMID 36613546, 2022).
lung squamous cell carcinoma (3 papers, 2021 to 2023). "The DSS of lung squamous cell carcinoma (LUSC) male patients with high FASN expression was significantly poorer than those with low FASN expression." (PMID 37696831, 2023).
lupus (3 papers, 2024 to 2026). "Loss of FASN significantly alleviated the disease in lupus-prone mice and inhibited the activation and differentiation of B cells." (PMID 39115936, 2024). "Inhibiting FASN-mediated lipid metabolism in B cells alleviates lupus in mice." (PMID 41280910, 2025). "Furthermore, compared with those in the control group, B cells from systemic lupus erythematosus (SLE) patients presented increased levels of fatty acid synthase and decreased levels of IL-17RB." (PMID 40536951, 2026). "The FASN inhibitor TVB-2640 can activate macrophages and DCs and significantly ameliorate imiquimod (IMQ)-induced lupus in mice, showing great potential, particularly in SLE." (PMID 41280910, 2025).
metastatic carcinoma (3 papers, 2015 to 2022). A carcinoma which has spread from the original site of growth to another anatomic site. "FASN expression was significantly different between primary and metastatic cancer (p = 0.008)." (PMID 26334757, 2015).
metastatic prostate carcinoma (3 papers, 2020 to 2024). A carcinoma that arises from the prostate gland and has spread to other anatomic sites. "Taken together, these data suggest that methylation could be a mechanism regulating FASN expression levels in primary tumors and metastatic prostate cancer." (PMID 38112617, 2024). "PPARG is a classic transcription factor triggered by ligand, activating lipid signaling by upregulating acetyl-CoA carboxylase (ACC), fatty acid synthase (FASN) and ATP citrate lyase (ACLY), and promotes the metastatic prostate cancer." (PMID 37932808, 2023).
non-Hodgkin lymphoma (3 papers, 2020 to 2022). Distinct from Hodgkin lymphoma both morphologically and biologically, non-Hodgkin lymphoma (NHL) is characterized by the absence of Reed-Sternberg cells, can occur at any age, and usually presents as a localized or generalized lymphadenopathy associated with fever and weight loss. "Similar metabolic variations with suppression of nucleotide metabolism accompanied by increased glycolytic activity were observed in our recent studies investigating the impact of fatty acid synthase (FASN) inhibition on the nucleotide metabolism in non-Hodgkin’s lymphoma." (PMID 36224623, 2022). "We have previously reported the occurrence of PI3K alterations and increased FASN expression in non-Hodgkin lymphoma (NHL)." (PMID 34765544, 2021). "In non-Hodgkin lymphoma cell lines, cross-talk between glycolysis and FASN-mediated lipid synthesis is shown to be PI3K/AKT pathway-dependent, in which inhibition of FASN activity impairs cellular glycolytic flux and vice versa." (PMID 32872164, 2020).
nutritional disorder (3 papers, 2016 to 2026). Any condition related to a disturbance between proper intake and utilization of nourishment. "It is probable, therefore, that decrease in the levels of THRSP, FASN, and FABP4 expression in the LowFe animals is an adaptation to a smaller quantity of iron, since iron deficiency, with or without anemia, harms thyroid metabolism." (PMID 27532424, 2016).
papillary thyroid cancer (3 papers, 2012 to 2023). "Histone methyltransferase KMT5A regulates the occurrence of papillary thyroid cancer in vitro and the expression of lipid metabolism molecules such as SREBP1, SCD (catalytic saturated fatty acids), FASN (fatty acid synthase), and ACC (acetyl CoA carboxylase)." (PMID 37305043, 2023).
primary effusion lymphoma (3 papers, 2021 to 2023). A large B-cell lymphoma located in the body cavities, characterized by pleural, peritoneal, and pericardial fluid lymphomatous effusions and that is always associated with human herpes virus-8 (HHV-8). "FASN is up-regulated in a PI3K-dependent manner in primary effusion lymphoma (PEL) and other types of non-viral B-NHLs." (PMID 36982568, 2023).
psoriasis (3 papers, 2024 to 2026). An autoimmune condition characterized by red, well-delineated plaques with silvery scales that are usually on the extensor surfaces and scalp. "Subsequent molecular biology experiments demonstrated that brusatol ameliorates psoriasis-associated dyslipidemia by modulating the AMPK-mediated SREBP-1c/FASN and PPARα/CPT1A signaling pathways." (PMID 41508030, 2026). "Therefore, inhibiting ACC1 and other core enzymes of FAS, including ACLY and FASN, represents an attractive therapeutic strategy for psoriasis." (PMID 40360755, 2025).
thyroid cancer (3 papers, 2013 to 2021). "Elevated FASN was identified in human breast, bladder, colon, head and neck, endometrium, lung, prostate, oesophagus, ovary, stomach, tongue and thyroid cancers." (PMID 23292678, 2013). "High expression of FASN in human liver, breast, colorectal, prostate, endometrial, ovary and thyroid cancer supports the hypothesis that FASN is essential for generating cell membranes during tumor cell proliferation." (PMID 25009654, 2014). "However, in rapidly proliferating cancer cells, such as liver, prostate, ovarian, breast, endometrial and thyroid carcinomas, FASN is overexpressed." (PMID 25009654, 2014).
Abdominal obesity (2 papers, 2020 to 2025). Excessive fat around the stomach and abdomen. "Next, we investigated the correlation between FASN expression and the abdominal obesity distribution, especially VAT% that serves as a more representative indicator than BMI to investigate individual adipose distribution of ccRCC patients." (PMID 33569391, 2020). "Additionally, elevated FASN mRNA expression is significantly correlated to the abdominal obesity distribution, especially VAT%, which is a significant predictor of a poor prognosis for ccRCC patients." (PMID 33569391, 2020). "Additionally, we revealed that elevated FASN mRNA expression was significantly correlated to abdominal obesity distribution, especially VAT%, which is also a significant predictor of a poor prognosis for ccRCC patients." (PMID 33569391, 2020).
acne (2 papers, 2024). An inflammatory process of the sebaceous glands which is characterized by comedones, nodules, papules and/or pustules on the skin. "In the research exploring potential therapeutic targets for acne, through Mendelian randomization (MR) analysis and colocalization analysis, we identified two proteins significantly associated with acne risk: FASN and TIMP4." (PMID 39297226, 2024). "For FASN, a negative β‐value (β = −0.264) suggests that increased genetically predicted levels of FASN correlate with a lower risk of acne (OR = 0.768, 95% CI: 0.676–0.872, p = 4.685E‐05), a finding that persisted after FDR correction (p = 0.039)." (PMID 39297226, 2024). "Similar to TIMP4, FASN may also influence the risk of acne onset through pathways such as sebaceous gland activity and inflammatory responses." (PMID 39297226, 2024). "Similarly, the PH4 for FASN was 0.8905, also denoting a high probability of a shared causal variant, underscoring the genetic link between these proteins and acne." (PMID 39297226, 2024). "Following the application of the Benjamini–Hochberg (B–H) method for FDR correction set at 0.05, only two proteins, FASN fatty acid synthase (FASN) and tissue inhibitor of metalloproteinases 4 (TIMP4), remained significantly associated with acne risk." (PMID 39297226, 2024). "FASN exhibited a protective effect against acne (OR = 0.768, 95% CI: 0.676–0.872, p = 4.685E‐05), while TIMP4 was associated with an increased risk (OR = 1.169, 95% CI: 1.103–1.241, p = 1.956E‐07)." (PMID 39297226, 2024). "Following multiple testing corrections using the Benjamini–Hochberg method, fatty acid synthase (FASN) and tissue inhibitor of metalloproteinases 4 (TIMP4) remained significantly associated with acne risk." (PMID 39297226, 2024). "Two novel acne associated loci, identified in this study, contain genes encoding enzymes involved in lipid metabolism: FADS1/FADS2 and FASN." (PMID 36922633, 2024). "For example, FASN can regulate the expression of inflammatory cytokines through the nuclear factor‐kappa B (NF‐κB) pathway, thereby participating in the inflammatory responses in the pathogenesis of acne." (PMID 39297226, 2024). "Existing studies suggest that FASN inhibitors also hold great potential in treating acne." (PMID 39297226, 2024). "According to a public report at the 2024 American Academy of Dermatology (AAD) annual meeting, ASC40, a Fatty Acid Synthase Inhibitor for treating acne, has completed preliminary clinical trials, showing that 10 days of ASC40 treatment can significantly reduce facial sebum palmitic acid levels." (PMID 39297226, 2024). "However, as Fatty Acid Synthase Inhibitors have not yet been formally recognized as an acne treatment medication and have not entered widespread clinical use, further research and observation are needed to evaluate their long‐term safety and efficacy." (PMID 39297226, 2024).
asthma (2 papers, 2023 to 2025). "Indeed, circulating iNKT cells from allergic asthma patients expressed significantly higher levels of ACC1, FASN, and PPARG than iNKT cells from healthy controls and nonallergic asthma patients." (PMID 37917548, 2023). "Thus, iNKT cells from allergic asthma patients express higher ACC1, FASN and PPARG levels and lower levels of a glycolysis, which is accompanied with higher levels of IL4 and IL13 than iNKT cells from healthy controls and nonallergic asthma patients." (PMID 37917548, 2023).
bladder transitional cell carcinoma (2 papers, 2021 to 2023). The most common morphologic subtype of urinary bladder carcinoma (over 90% of cases). "Moreover, inhibition of FASN expression can suppress the migration capacity of bladder transitional cell carcinoma by activating AKT." (PMID 34819038, 2021). "Besides, high expression of FASN could predict poor OS and PFI in male patients with bladder urothelial carcinoma (BLCA) and kidney renal clear cell carcinoma (KIRC)." (PMID 37696831, 2023).
Blindness (2 papers, 2018 to 2021). Blindness is the condition of lacking visual perception defined as a profound reduction in visual perception. "Here, we demonstrate that deleting the de novo lipogenic enzyme fatty acid synthase (FAS) from the neural retina, but not the vascular retina, results in progressive neurodegeneration and blindness with a temporal pattern resembling rodent models of retinitis pigmentosa." (PMID 29321376, 2018).
Burkitt lymphoma (2 papers, 2020 to 2024). A rare form of malignant mature B-cell non-Hodgkin lymphoma. "USP2a is detected in LMP1-positive Burkitt’s lymphoma (BL) cells and mediates the stabilization of fatty acid synthase (FASN)." (PMID 39664521, 2024). "Lipid metabolism, as well as enzymes involved in lipogenesis, including FASN, has been reported to be dysregulated in Burkitt lymphoma, resulting in the accumulation of multiple lipid vacuoles in the cytoplasm, a morphological characteristic of Burkitt lymphoma cells." (PMID 32046309, 2020).
colon adenocarcinoma (2 papers, 2022 to 2025). "In summary, these data suggest that CS is highly expressed in CRC, and there is a positive correlation between CS and FASN expression at mRNA and protein levels in colon adenocarcinomas." (PMID 35742953, 2022). "To translate our findings to human cancer, we analyzed The Cancer Genome Atlas RNA-Seq data and identified a highly significant positive correlation between FASN and CS gene expression in human colon adenocarcinomas." (PMID 35742953, 2022).
COVID-19 (2 papers, 2021 to 2023). A disease caused by infection with severe acute respiratory syndrome coronavirus 2. "Among them, six genes (CXCR4, ENO1, FASN, GATA6, PDK1 and TUBB3) have been reported to be associated with the pathological mechanism of COVID-19 and OA." (PMID 37291167, 2023). "ENO1 and TUBB3 were found to be probably related to the progression of OA, while FASN and GATA6 may participate in COVID-19." (PMID 37291167, 2023).
diabetic retinopathy (2 papers, 2023 to 2024). "Moreover, it has been reported that the inhibition of FASN impaired EC angiogenesis via mTOR malonylation in diabetic retinopathy." (PMID 37414769, 2023).
energy metabolism disorders (2 papers, 2024 to 2025). "Previous studies have shown that FASN overexpression promotes the accumulation of lipids in liver cells and induces oxidative damage to liver tissue, leading to lipid and energy metabolism disorders." (PMID 40124784, 2025). "Previous studies have shown that the downregulation of FASN can alleviate energy metabolism disorders induced by potassium dichromate in LMH cells." (PMID 39199852, 2024).
esophageal squamous cell carcinoma (2 papers, 2024 to 2025). Esophageal squamous cell carcinoma (ESCC) is a type of esophageal carcinoma (EC) that can affect any part of the esophagus, but is usually located in the upper or middle third. "In esophageal squamous cell carcinoma, NAT10 stabilizes the expression of fatty acid synthase (FASN) by mediating ac4C modification, thereby promoting the M2 polarization of macrophages." (PMID 40767620, 2025).
gallbladder cancer (2 papers, 2024 to 2025). "Other studies indicated that changes in fatty acid synthase (FASN) promotes gallbladder cancer progression through PI3K/AKT signaling." (PMID 38519939, 2024).
gastrointestinal stromal tumor (2 papers, 2025). "For instance, FASN inhibitors enhance the accumulation of LC3 II in gastrointestinal stromal tumors." (PMID 39567194, 2025).
gestational diabetes (2 papers, 2016 to 2025). Carbohydrate intolerance first diagnosed during pregnancy. "Subsequent research will delve into the effects of reducing CCNB1 on additional essential metabolic controllers like AMPK, HK2, and FASN, in order to gain a more comprehensive understanding of its broader involvement in metabolic control during gestational diabetes." (PMID 39822992, 2025).
glomerulosclerosis (2 papers, 2020 to 2024). A hardening of the kidney glomerulus caused by scarring of the blood vessels. "miR-544 can directly target the mRNA of FASN, and subsequently inhibit glomerulosclerosis and inflammation, thereby alleviating diabetic kidney injury, suggesting that FASN is involved in the pathogenesis of DN and that targeting FASN could be a potential approach to treat DN." (PMID 38272906, 2024). "Fatty acid accumulation (FAC) was also induced by DKD, fatty acid synthase (FASN) is not only the vital lipogenic enzyme to FAC, but also an upregulated molecule that contributes to glomerulosclerosis and renal inflammation." (PMID 33574750, 2020).